CCL5 (C-C motif chemokine ligand 5)
Diseases named in the same sentence as CCL5 in open-access papers (continued):
Sharing a sentence is not in itself a finding about the gene and the disease.
atherosclerosis (continued). "Heterophilic interactions between CXCL4 and CCL5 promote neutrophil recruitment in an LPS-induced acute lung injury model and accelerate atherosclerosis by triggering monocyte arrest on the endothelium." (PMID 37446102, 2023). "Increased serum levels of CCL5 and CXCL10 are associated with human atherosclerotic plaque progression and stability, and the inhibition of either cytokine reduced atherosclerosis in animal models." (PMID 36247423, 2022). "These literatures demonstrate that both CXCL10 and CCL5 play critical roles in atherosclerosis development, and their inhibition is an effective anti-atherogenic approach." (PMID 36247423, 2022). "As an overview, the early stages of atherosclerosis involve the secretion of chemokines by activated platelets and activated smooth muscle cells, such as C-C motif chemokine 5 (CCL5) that promote infiltration of monocytes and neutrophils." (PMID 35509276, 2022). "The recruitment of monocytes results in the enhanced infiltration of macrophages at an early-stage atherosclerosis, which can be mediated by myeloid cell-derived CCL5." (PMID 35559253, 2022). "Regulated on Activation, Normal T cell Expressed and Secreted (RANTES), also known as chemokine ligand (CCL5), is a proinflammatory cytokine generated by activated T cells, macrophages, and platelets that plays a role in atherosclerosis pathogenesis." (PMID 36555898, 2022). "For instance, previous studies indicated that CCL5/RANTES and its receptor–CCR5 are associated with T2DM, glucose intolerance, obesity, and atherosclerosis." (PMID 36430701, 2022). "CCL5 is involved in a wide range of inflammatory processes, including advanced atherosclerosis and myocardial reperfusion injury." (PMID 35795669, 2022). "Blockade of type-I IFN signaling in macrophages suppressed atherogenesis, while IFN-β treatment accelerated atherosclerosis through the induction of the chemokine CCL5 which leads to increased monocyte recruitment to plaques." (PMID 35224060, 2022). "Consistent with our data, previous studies show that CCL3 and CCL5 are associated with LDL-c and atherosclerosis." (PMID 36231033, 2022). "It has been reported that the chemokine CCL5 assists in the recruitment of monocytes to the intima in the early stages of atherosclerosis and promotes the conversion of macrophages." (PMID 35702353, 2022). "Our study also found that new genes like CSF2RB, IL1RN, CCL5, MMP9, CD53, NCF2 and TLR2 associated with Inflammation present high expression both in psoriasis and atherosclerosis." (PMID 34122426, 2021). "In atherosclerosis, macrophages are the major CCL5-expressing cells in the atherosclerotic plaque, CCL5 expression in macrophages is promoted by IFN-γ." (PMID 34122426, 2021). "CD8α+ dendritic cells aggravate atherosclerosis, likely by inducing Th1 cell response, which promotes CCL5 expression in macrophages and increased infiltration of leukocytes and lesion inflammation." (PMID 34122426, 2021). "Soon after, a study investigated the effects of systemic CCL5 antagonism via Met-RANTES for 14 weeks in a diet-induced mouse atherosclerosis." (PMID 33503867, 2021). "Combination of CXCL4 and CCL5 was shown to exacerbate disease in a mouse model of atherosclerosis, and CXCL12 in combination with HMGB1 enhanced monocyte recruitment in a mouse model of tissue damage." (PMID 33123134, 2020). "This protein is known to regulate the transcription of the C-C chemokine 5 (CCL5/Rantes) gene which serves as a chemoattractant during inflammation and atherosclerosis." (PMID 32455723, 2020). "To date, the CC-chemokine family has been strongly implicated in atherosclerosis with a host of CC-chemokines including MCP-1 (CCL2), RANTES (CCL5) and MIP-1α (CCL3) detected in human atherosclerotic lesions." (PMID 28282403, 2017).
atherosclerosis (continued). "Expression of key chemokines previously linked to atherosclerosis, including CCL2 and CXCL10 as well as CCL5, was significantly attenuated by AVE0991 treatment, in the PVAT of ApoE−/− mice, while no change was seen in the aortic wall itself." (PMID 27935022, 2017). "Various chemokines including CCL2 and CCL5 were shown to control the recruitment of myeloid cells to the aortas during atherosclerosis progression." (PMID 28536468, 2017). "As an example, the functional potential of chemokine synergy was demonstrated in vivo using peptides that inhibit the CXCL4/CCL5 heterodimer in a mouse atherosclerosis model." (PMID 28368308, 2017). "RANTES also known as chemokine ligand 5 (CCL5) is a chemokine that has a role in atherosclerosis and found in large quantities in platelet α-granules." (PMID 27403440, 2016). "CCL5 is upregulated in the injured vessels via activation by platelets during the process of atherosclerosis." (PMID 25889019, 2015). "CCL5 acting at CCR5 was considered to be crucial to monocyte recruitment during the early atherosclerosis." (PMID 26688689, 2015). "CCL5 acting at CCR5 is considered to be crucial to monocyte recruitment during development of atherosclerosis." (PMID 26688689, 2015). "CCL5 levels were assessed in plasma from arsenic-exposed apoE-/- mice after 8 and 13 weeks, time points where significant arsenic-enhanced atherosclerosis is observed." (PMID 26332580, 2015). "Chemokines such as MCP-1, GM-CSF, PDGF-BB, IL-6 and CCL-5 are known to promote atherosclerosis and myocardial ischemia." (PMID 26246800, 2015). "The expression of CCL5 in ascending atherosclerotic aorta of patients with atherosclerosis was examined by immunohistochemistry." (PMID 25889019, 2015). "PMPs were identified as transcellular delivery systems for chemokines such as CCL5 promoting monocyte recruitment and atherosclerosis." (PMID 25152735, 2014). "Of these, CXCL9, CXCL10, CCL5, CCL8, CRCL2, Cd74 and IRF8 have previously been implicated in atherosclerosis." (PMID 25478796, 2014). "The heparin binding motif in CCL5 in the 40s loop is important for its biological activity and contributes to atherosclerosis." (PMID 25152735, 2014). "One of the ligands for the CCR5 receptor, CCL5 or RANTES, has also been shown to be involved in unstable angina pectoris, which usually results from atherosclerosis." (PMID 24832521, 2012). "Our workgroup previously showed the synergistic interaction of CXCL4 and CCL5 to accelerate atherosclerosis by triggering monocyte arrest on endothelium." (PMID 22807925, 2012). "Taken together, all data indicate an important role for CCL5/CCR5 signaling pathway in the pathogenesis of atherosclerosis." (PMID 22292067, 2012). "Another study additionally confirms [44AANA47]-CCL5 as a potential therapeutic agent against atherosclerosis." (PMID 22807925, 2012). "CCL5 has been indirectly shown to be atherogenic: antagonism of its receptor with a methionine-retaining CCL5 isoform slows atherosclerosis in vivo." (PMID 22022522, 2011). "While MCP-1 is now regarded as a key inflammatory marker, CC chemokine ligand-5 (CCL5/RANTES) has in recent years emerged as a potentially therapeutic target in the prevention of atherosclerosis." (PMID 22011432, 2011). "In the present study, we observed that patients with CAS had significantly elevated serum levels of CX3CL1, CXCL12, CCL19, CCL21, CCL2, and CCL5 compared to control individuals, suggesting that these chemokines are intricately involved in the initiation and progression of atherosclerosis." (PMID 40236901, 2025). "Blockade of CCL5 or its highest affinity receptor (CCR5) significantly attenuates the atherosclerosis process, as well as vascular inflammation in cases of lipodystrophy and inflammation of perivascular adipose tissue (PVAT) in hypertension, as demonstrated in in vivo and in vitro studies." (PMID 40859641, 2025). "CCL5 promotes the recruitment of monocytes during early stages of atherosclerosis." (PMID 37476204, 2023).
atherosclerosis (continued). "Although CCL5 was identified as a major contributor to the inflammatory response induced by plasma with atherosclerosis and, as such, it could be directly targeted, inhibition of CCL5 did not fully reverse the response in CD1c+ DCs." (PMID 37771373, 2023). "The increased levels of Trem2hi macrophages and Ccl5+ T cells may, in part, explain the increased atherosclerosis progression in the Tie2-deleted mice." (PMID 37476204, 2023). "Still, some chemokines may be useful as biomarkers since augmented levels of CCL5 or CXCL12 correlate with the severity of atherosclerosis or CAD respectively." (PMID 35600479, 2022). "Other causes of variability may be found in pre-existing conditions, such as atherosclerosis; indeed, CCL5 was found to be involved in atherosclerotic lesion formation." (PMID 36077361, 2022). "MetCCL5 serves as a specific CCL5 antagonist by binding to the CCL5 receptor on monocytes, leading to inhibition of atherosclerosis in mouse models, but its effect on ECs is unknown." (PMID 36247423, 2022). "Inhibition of CCL5 reduces myocardial reperfusion in atherosclerosis mice." (PMID 35795669, 2022). "Infusion of activated platelets into hyperlipidemic mice resulted in an accelerated development of atherosclerosis, which could be attributed in part to increased immobilization of CCL5 onto the atherosclerotic vessels." (PMID 34298951, 2021). "While the development of atherosclerosis was associated with increased plasma levels of IL-1β, TNFα, IL-6, monocyte chemoattractant protein-1 (MCP-1), and C-C motif chemokine ligand-5 (CCL-5), increased MCP-1 and CCL-5 were specifically observed in SCI mice versus uninjured controls." (PMID 34571804, 2021). "CCL5 is increased in atherosclerosis, Myocardial infarction, and RHD." (PMID 34926598, 2021). "RANTES (also known as CCL5) belongs to the family of CC chemokines and has strong chemoattractive activity for T lymphocytes and macrophages, and its role in the development of atherosclerosis has been confirmed in numerous studies." (PMID 33669450, 2021). "Additionally, increasing IL-10, IL-4, IL-13, and TGF-β and reducing IL-1β, Il-6, TNF-α, CCL3, CCL4, and CCL5 can slow the progression of atherosclerosis." (PMID 32346605, 2020). "Furthermore, it is interesting to note that there is a correlation between plasma CCL5 levels and the progression of atherosclerosis in patients after acute coronary syndrome." (PMID 31191301, 2019). "In summary, the role of CCL5 was more important than CCR5 for atherosclerosis." (PMID 26688689, 2015). "Besides, the ligands of CCR5, including CCL5 (regulated upon activation, normal T-cell expressed and secreted, RANTES), have the important role in the initiation and progression of atherosclerosis." (PMID 26688689, 2015). "CCL5 antagonist inhibited atherosclerosis progression in mouse models." (PMID 26688689, 2015). "Moreover, injection of activated platelets in atherosclerosis-prone mice resulted in a P-selectin-dependent endothelial deposition of CCL5 and CXCL4 and increased lesion formation." (PMID 25152735, 2014). "Interestingly, in these latter cells, NOV induces CCL-2 and CCL-5 (unpublished data), which are involved in the immune-inflammatory response of atherosclerosis." (PMID 23785511, 2013). "Neutralization of IL-17A not only reduced the atherosclerotic plaques but also down regulated IL-6, TNF-α and CCL5 that suggests that regulation of these cytokines may be interconnected in atherosclerosis." (PMID 23437105, 2013). "Chemokine CCL5 has been shown to be involved in atherosclerosis progression." (PMID 22292067, 2012). "Therefore, the present study aimed to investigate the potential role of H2S in atherosclerosis and the underlying mechanism with respect to chemokines (CCL2, CCL5 and CX3CL1) and chemokine receptors (CCR2, CCR5, and CX3CR1) in macrophages." (PMID 22815945, 2012).
atherosclerosis (continued). "We hypothesised that its relevance for atherosclerosis should be reflected by associations between CCL5 gene variants, RANTES serum concentrations and protein levels in atherosclerotic plaques and risk for coronary events." (PMID 22162987, 2011). "Ccl5 is homologous to human CCL5 (C-C motif chemokine ligand 5), a key pro-inflammatory chemokine that induces in vitro migration and recruitment of a variety of cells, including T cells, and plays a role in a variety of biological processes including cancer and atherosclerosis." (PMID 37193034, 2023). "Hence, increased levels of CCL5 may act as a biomarker for the severity of atherosclerosis and may even be a potent therapeutic target for SMC proliferation and phenotype switching." (PMID 35600479, 2022). "The chemokine ligand 5 (CCL5, also known as regulated upon activation, normal T cell expressed and aresumably secreted (RANTES)), a ligand of CCR5, has been implicated in the pathophysiology of atherosclerosis through the mediation of VSMC phenotype switching and macrophage recruitment." (PMID 32727125, 2020). "Among this broad range of chemokines, the chemokine CC-motif ligand 5 (CCL5, also known as RANTES) is of particular interest, because it is one of the most expressed chemokines by activated platelets and plays a prominent role in the development of atherosclerosis." (PMID 32817341, 2020). "CCL2 and CCL5 are primarily involved in monocyte and SMC recruitment, promoting the formation of atherosclerosis, whereas CCL19 and CCL21 facilitate macrophage emigration, thereby promoting the regression of advanced plaques." (PMID 40236901, 2025). "CCL5 deposition then enhances monocyte recruitment by inflammatory aortic ECs, which allows it to serve as a biomarker for chronic CAD and atherosclerosis initiation." (PMID 41302081, 2025). "The expression patterns of the major migration-driving chemokines MCP-1 (CCL2), MIP-1α (CCL3), MIP-1β (CCL4), RANTES (CCL5), and fractalkine (CX3CL1) in patients with atherosclerosis were of particular interest in this study." (PMID 38256102, 2024). "Our results were verified by qPCR for the selected cytokines involved in immune cell activation and migration (CCL2, CCL3, CCL4, CCL5, CX3CL1), representing potential therapeutic targets in atherosclerosis." (PMID 38256102, 2024). "Up-regulated DEGs of this gene signature included T-cell development, growth and proliferation genes (BATF, CCL5, CD2, EOMES) and F2R, a recognized genetic locus influencing clinical CVD and atherosclerosis development." (PMID 37205656, 2023). "Monocyte chemotactic protein 1 (MCP-1), Fractalkine (CX3CL1), RANTES (CCL5), and eotaxin (CCL11) are involved in the development of atherosclerosis." (PMID 36865551, 2023). "In both PSA and atherosclerosis CD8+ C3 T cells, expression profiles displayed a similar phenotype with high expression of T cell effector genes—for example, CCL5, GZMH, GZMA, GZMK and NKG7." (PMID 38665903, 2023). "Chemokines such as CCL2, CCL5, and CXCL10 play a crucial role in the early stages of atherosclerosis via EBD as well as via atherogenic phenotype switching of VSMCs." (PMID 36497143, 2022). "For example, heterodimerization of CCL5 with CXCL4 (platelet factor 4) has a synergetic effect on monocyte adhesion, whereas disruption of this heterodimer attenuates atherosclerosis development." (PMID 32817341, 2020). "In atherosclerosis, many studies have supported the role of the chemokine receptor CCR5 and its ligands CCL3, CCL4, and CCL5 in triggering the progression of atherosclerosis, particularly in later stages of plaque." (PMID 32346605, 2020).
atherosclerosis (continued). "In a previous study, we have demonstrated a pathophysiologic relevance for the heterophilic interaction of CCL5 and CXCL4 in the progression of atherosclerosis." (PMID 30006564, 2018). "The knockout and transgenic studies provide convincing proof that individual chemokine-chemokine receptor signalling pathways are important in atherosclerosis, particularly the CCL2/CCR2, CCL5/CCR5 and CX3CL1/CX3CR1 pathways." (PMID 28282403, 2017). "The ‘M3’ chemokine binding protein inactivates key chemokines involved in atherosclerosis (e.g. CCL2, CCL5 and CX3CL1)." (PMID 28282403, 2017). "The most elaborately studied chemokines in atherosclerosis, CCL2/MCP-1 and CCL5/RANTES, have been implied to reflect the burden of atherosclerotic lesions in cardiovascular disease patients." (PMID 23029252, 2012). "The significance of chemokines (CCL2 [monocyte chemotactic protein-1], CCL5 [RANTES] and CX3CL1 [fractalkine]) and their receptors (CCR2, CCR5 and CX3CR1) in atherosclerosis has been demonstrated in animal models and clinical studies." (PMID 22815945, 2012). "Injection of activated platelets into the tail vein of atherosclerosis prone mice results in exacerbated atherosclerotic lesions and increased endothelial deposition of CXCL4 and CCL5 dependent on the presence of P-selectin." (PMID 22807925, 2012). "Compelling evidence for in vivo dimer function also comes from a recent study that has shown CCL5 and CXCL4 form heterodimers, and design of peptides that disrupt this interaction inhibit atherosclerosis in hyperlipidemic mice." (PMID 20668677, 2010). "While CXCL4 has been amply characterized by us and others as a pro-atherogenic platelet chemokine, in part also via its intriguing capacity to hetero-oligomerize with CCL5, very little is known about the role of CXCL4L1 in chronic inflammatory diseases and atherosclerosis." (PMID 36094626, 2022). "Unlike CXCL4, CXCL4L1 did not bind to CCL5 and did not enhance atherosclerosis in transgenic mice with CXCL4 modified to CXCL4L1, indicating that CXCL4L1 has reduced inflammatory potential, at least during plaque development." (PMID 35054772, 2022). "Apart from CCR5 and CCR1, CCR3 has been shown to be overexpressed in CD68+ macrophage rich areas of human atherosclerotic lesions, however there is not sufficient information regarding its roles in atherosclerosis, especially through interaction with CCL5." (PMID 33503867, 2021). "Importantly, the use of an anti-inflammatory salicylate drug was found to prevent SCI-induced exacerbation of atherosclerosis, possibly via the reduction in TNFα, MCP-1, and CCL-5 plasma levels." (PMID 34571804, 2021). "It has been known that platelets are also involved in the development and manifestation of atherosclerosis by secreting chemokines including CXCL4 or platelet factor 4, CCL5, CXCL12 to recruit monocytes or neutrophils to promote local inflammatory processes at sites of vascular injury." (PMID 34901005, 2021). "In addition to CCL5, CCL3 and CCL4 have also been reported to participate in the process of atherosclerosis." (PMID 32194402, 2020). "Thus, further studies are needed to use maraviroc for decreasing atherosclerosis or intimal hyperplasia.In our study, PPB induced downregulation of CCL5/CCR5 pathway." (PMID 32727125, 2020). "Based on the evidences that CCL5/CCR5 pathway involves in progression of atherosclerosis or intimal hyperplasia, several studies reported that maraviroc, an antagonist of CCR5, showed decreasing atherosclerosis or intimal hyperplasia." (PMID 32727125, 2020). "Among them, only CCR5 was related to the progression of atherosclerosis, as some of its ligands, such as CCL3, and CCL4, CCL5, could be detected in atheroma plaques." (PMID 32911750, 2020).